CD5 (CD5 molecule)
Diseases named in the same sentence as CD5 in open-access papers (continued):
Sharing a sentence is not in itself a finding about the gene and the disease.
tumor (continued). "We next evaluated tissue from tumor bearing mice (tumor mass, spleen, intestine and kidney) by immunohistochemical analysis for the expression of CD3, CD5, CD19, CD20, CD23, CD45, CD79a, Ki-67, cyclin D1, and Pax5." (PMID 24722054, 2014). "Immunohistochemically, the tumor cells were cytokeratin -, vimentin +, CD3+, CD45RO+, CD5-, CD7-, CD4-, CD8-, CD10-, CD20-, CD30-, CD79a-, CD138-, CD56-, granzyme B-, TIA-1 cytotoxic granule-associated RNA binding protein (TIA-1) + and ALK-." (PMID 22931631, 2012). "The tumor cells are positive for one or more pan-T-cell antigens (CD2, CD3, CD5, or CD7) and CD20 with monoclonal rearrangements of TCR γ or β without rearrangement of the IgH gene." (PMID 23031227, 2012). "Immunohistochemically, tumor cells showed CD3+, CD45RO+, CD5-, CD7-, CD4-, CD8-, CD10-, CD20-, CD30-, CD79a-, CD138-, CD56-, granzyme B-, TIA-1+ and ALK-." (PMID 22931631, 2012). "These tumor cells were positive to the surface markers CD19, B220, CD5 and IgM, and also expressed the co-stimulatory molecules CD80, CD86 as well as CD117." (PMID 21269511, 2011). "PTCL is diagnosed when tumor cells express the mature T cell antigens CD2, CD3, CD4, CD5, CD6, or CD7 on immunohistochemical staining." (PMID 21310044, 2011). "The combination of anti-CD5 and anti-CD71 also showed very favourable results, with only 1 mouse out of 8 developing a subcutaneous tumour, while 7 animals (88%) were apparently cured." (PMID 21504579, 2011). "The downmodulation of CD6 and CD5 by itolizumab independent of CD318 expression suggests a regulatory mechanism of anti-tumor responses." (PMID 40391211, 2025). "Given the scarcity of truly tumor-specific antigens (absent on normal cells) and substantial tumor heterogeneity, pan-T-cell antigens (such as CD5 and CD7) have emerged as the predominant targets in clinical trials for T-cell malignancies." (PMID 41250215, 2025). "Furthermore, aging significantly impacted the immune infiltrate/tumor composition, with a substantial decrease in the density of specific immune cells detected by CD3, CD5, CD8, and CD20 in all tumor areas (P < 0.042)." (PMID 40584290, 2025). "Given the patient’s history of CLL, those B-cell aggregates were further evaluated for potential SLL deposits and demonstrated positivity for CD20, CD5, and LEF-1 (weak positivity), being most consistent with CLL/SLL as opposed to tumor-associated TLS." (PMID 41333460, 2025). "Malignant CD4 cells from tumor-stage lesions did not have significantly different CD5 expression compared to healthy controls (log2 fold change of −0.24, adjusted p-value > 0.05)." (PMID 41226451, 2025). "The various hormone receptor profiles showed the tumor was negative for CD5, CK5/6, c-kit, and p63, while positive for estrogen receptor (ER), progesterone receptor (PgR), and GATA-3." (PMID 41035587, 2025). "In addition, homing and activation-related proteins L-selectin (CD62L), CD5 and CD69 in T cells were down-regulated to varying degrees in G-MDSCs group, which suppressed the antitumor immune activity of tumor-infiltrating T cells." (PMID 38169579, 2024). "The effect of administering an anti-CD5 antibody to block or reduce CD5 function as an immune checkpoint blockade to enhance T cell anti-tumour activation and function in vivo has not been explored." (PMID 38487537, 2024). "When compared to wild-type CD5-CAR-T, CRISPR-Cas9-based KO CD5-CAR T enhances anti-tumor efficacy with improved CAR-T activation and proliferation, which may be driven in part by reduced fratricide." (PMID 39456582, 2024). "Histologically, the nodal tumor was largely diffuse with neoplastic small atypical lymphocytes co-expressing CD5, CD10, and CD20, but not CD23 or cyclin D1." (PMID 38535060, 2024). "CAR-M targeting CD19, CD22, HER-2, CD5, and carcinoembryonic antigen-related cell adhesion molecule 5 (CEACAM5) have been developed to fight against solid tumors and hematopoietic malignancies with improved tumor control and significant activation of TME." (PMID 38195534, 2024).
tumor (continued). "FHVH-derived CD5/CD7 bispecific CAR-T cells with CD5 and CD7 deletion had showed potent antitumor activity against T cell malignancies and tandem CARs could be conducive to mitigating tumor antigen escape." (PMID 39462383, 2024). "Anticipating that the tumor environment in CLL patients may affect SIGLEC10 expression, we also included normal naïve CD5− B cells, naïve CD5+ B cells, and CD27+ memory B cells from 5 age‐matched healthy donors." (PMID 37424400, 2023). "CD5 and CD10 were used to distinguish T cells from tumor cells in this study." (PMID 37488603, 2023). "However, from a prognostic perspective, CD5, SLCO1B1, and CD79A have been demonstrated to have protective value in various tumors, whereas ETV5, FZD7, SNX7, and SLC1A7 are involved in tumor progression." (PMID 37680641, 2023). "The increase in the frequency of PD-1+ and IgM+CD5+ B cells was only observed in subcutaneous tumors but not tumor-draining lymph nodes or spleen on the same tumor-bearing mice." (PMID 37035195, 2023). "Formalin-fixed, paraffin embedded tissue sections are stained with haemotoxylin and eosin (H&E) to evaluate tumour morphology, and immunohistochemical (IHC) stains with antibodies directed against CD3, CD5, CD20 and CD79α are used to differentiate between T and B cell lineage." (PMID 35882984, 2023). "CD5-CAR-T NK cells significantly reduced but did not eliminate the tumor, while the antitumor activity of CD5-CAR-NK NK cells was robust, leading to elimination of the tumor." (PMID 35158792, 2022). "Similarly, B1a Bregs (CD19+CD5+CD43+) have been described to use IL-10 to inhibit IFNγ and TNFα production by CD8+T cells thus negatively regulating tumour immunity against melanoma cells." (PMID 35350071, 2022). "Flow cytometric detection of human blasts (CD45+/CD19+ for B-ALL and CD45+/CD5+ or CD45+/CD7+ for T-ALL, based on surface marker phenotyping in the original tumor material) showed engraftment in all but one (patient #0031) patient sample, resulting in an engraftment rate of 94.4%." (PMID 35011712, 2022). "The fratricide-resistant FHVH-derived CD5/CD7 bispecific CAR-T cells have potent antitumor activity against T-cell malignancies, and tandem CARs are more effective than dual CAR in preventing tumor escape in heterogeneous leukemic cells." (PMID 35332132, 2022). "Tumor cells were identified as CD19+CD5+B220lo by FCM, alongside normal B cells (CD5-B220hi)." (PMID 35858562, 2022). "Due to the unselective elimination of normal T cells and malignant cells, pan-T cell antigen-targeting CAR-T cells, such as CD5, CD7, and CD3 T cells, will most likely be useful as a temporary tumor burden-control strategy instead of a permanent treatment option." (PMID 35882880, 2022). "In tumor microenvironment, CD5+ non-DE tumor revealed increased proportion of immunosuppressive M2 macrophages and enhanced pathways related to macrophage activation and migration." (PMID 36276140, 2022). "Percent tumor cell staining was recorded (Glut-1, CD5, CD117); loss of expression (BAP1, mTAP) was considered if essentially all tumor cells were negative; TdT was recorded as thymocytes present or absent (including rare thymocytes)." (PMID 35565429, 2022). "CD5/CD7 bispecific CAR-T cells selectively killed tumor cells in a dose-dependent manner, but not CD5-CD7- Raji, demonstrating that CD5/CD7 bispecific CAR-T cells maintain good specificity." (PMID 35332132, 2022). "Immunohistochemically, the tumor cells are usually positive for pan-T-cell markers (CD2, CD3, CD5, and CD7), although one or several (particularly, CD5 or CD7) may be downregulated or absent." (PMID 36010351, 2022). "CD4(2/20) and B cell markers, like CD20(1/20) and CD79α(1/20) were positive in scattered tumor cells; whereas CD5 was negative in all cases." (PMID 34895266, 2021). "ITLPD-GI tumor cells typically exhibit a CD2+, CD3+, CD5+, and CD4+ or CD8+ phenotype." (PMID 34830926, 2021).
tumor (continued). "The IHC analysis of the CASTLE tumor shows a strong positive staining with CD5, p63, and cytokeratin but negative staining with thyroglobulin, TTF1, and calcitonin." (PMID 34399813, 2021). "In these common variants of T-CUS, loss of CD5 and/or CD7 is frequently encountered and should not by itself raise concern for neoplasia." (PMID 33673033, 2021). "MEITL often occurs in elderly males and has non-specific digestive symptoms, with CD3+/CD8+/CD56+/CD5− monomorphic medium-sized tumor cells and obvious epitheliotropic performance." (PMID 34895266, 2021). "These CD5 CAR T cells potently lysed CD5+ malignant T-cell lines and primary tumors in vitro at higher or comparable rates than previous reports, while significantly controlling tumor expansion and improving survival in T-ALL xenograft models." (PMID 33081391, 2020). "Flow cytometric analysis of tumor-infiltrating cells showed a dominant population of B220+CD19+CD5− B-cell population (data not shown)." (PMID 32170099, 2020). "In addition, age had a significant effect on the composition the tumor/immune infiltrate, including a lower density of certain immune cells identified using CD3, CD5, CD8 and CD20, which was significant in all tumor regions (P < 0.042)." (PMID 33597950, 2020). "Moreover, immunohistochemical analysis revealed that tumor cells were positive for CD20, CD79a, PAX5, CD21, and CD23 and expression of CD3, CD5, and CD8 were observed in reactive T lymphocytes surrounding tumor cells." (PMID 33585230, 2020). "Regardless of that, low CD5 on T cells within tumors can conceivably lead to increased anti-tumor immune activity." (PMID 33584650, 2020). "Because sufficient CD19+CD5+ cells infiltrated in tumour tissues can't be acquired for analysis of distinct CD1d expression levels, we only quantified the frequency of CD19+CD5+ cells in tumour tissues and peripheral blood." (PMID 30467955, 2019). "Eleven of 121 cases(9.1%) stained positive for CD5, 10 occurring in men, with no significantdifferences in age, mean Ki67 expression, tumor site, or COO betweenCD5-positive and negative cases." (PMID 31045473, 2019). "The tumour cells of LELC and SCC showed positivity for CD5 and CD117." (PMID 29945642, 2018). "This evidence suggests that CD5, along with PD-1 and CTLA-4, may be a potential target to specifically modulate T cell Ca2+ mobilization in an immunosuppressive tumor setting." (PMID 29701673, 2018). "In addition, there was an increase in the CD19+ CD5+ B cell compartment after CRT, which is considered critical regarding the promotion of further tumor growth." (PMID 29464038, 2018). "The present work further supports available evidence on the involvement of CD5 –a negative modulator of T-cell activation- in the fine-tuning of immune responses in general and of anti-tumor responses in particular." (PMID 29296231, 2017). "The expression of marker CD5 by CASTLE cells, along with Hassall's corpuscles, may be highly characteristic of the tumour." (PMID 27110248, 2016). "We performed in vitro cellular and molecular biology assessments in primary CD5+ B lymphocytes obtained from a cohort of 80 CLL patients, and we assessed, in a CLL-xenograft mouse model, the in vivo capacity of the CD47 agonist peptides to reduce tumor burden." (PMID 25734483, 2015). "This may suggest the activated but reprogrammed BCR signaling in CD5+ DLBCL patients, and the role of CD5 expression in mitigating BCR signaling, and promoting tumor cell survival by previous studies." (PMID 25760242, 2015). "In one study comparison of 11 de novo CD5+ DLBCL and 9 CD5− DLBCL cases showed upregulation of integrin-β 1 and/or CD36 adhesion molecules, which were confirmed by immunohistochemistry (IHC) to be expressed in tumor cells and vascular endothelia, respectively." (PMID 25760242, 2015).
tumor (continued). "There is also a striking difference in vitro in the behaviour of T cell clones derived from tumour-infiltrating lymphocytes in that only CD5-negative clones are activated by tumour cells expressing low levels of cognate MHC/peptide complexes." (PMID 25237383, 2014). "Additionally, the up-regulation of CD5, CD24, CD70, CD226 and PDCD1 (PD-1) that usually express on the surface of T cells, B cells, dendritic cells, NK cells, and tumor cells have also been observed." (PMID 23191987, 2012). "For the anti-CD5 murine IgG2a antibody, additional control experiments were performed with mice bearing the wild type JOK1 tumour that does not express measurable amounts of CD5." (PMID 21504579, 2011). "The anti-CD5 treatment resulted in 4 months survival without any sign of tumour in 9 of 21 mice (43% mice), while tumour growth delay of about 14 days was observed in the 12 other mice." (PMID 21504579, 2011). "In contrast with these discrete and heterogeneous in vitro effects, in vivo the three mAbs demonstrated marked anti-tumour efficacy and prolongation of mice survival in two models of SCID mice, grafted either intraperitoneally or intravenously with the CD5 transfected JOK1-5.3 cells." (PMID 21504579, 2011). "This suggests the emergence of CD5-negative malignant subpopulations in MF tumor lesions." (PMID 41226451, 2025). "Notably, approximately 94.3% of malignant CD4 T-cells in tumor-stage lesions did not express CD5, compared to only 76.6% of malignant CD4 T cells from patch/plaque MF lesions." (PMID 41226451, 2025). "Our work suggests CD5 may be a viable therapeutic target in MF with patch/plaque presentations but may not be as effective in advanced stages of MF with tumor presentations." (PMID 41226451, 2025). "Immunohistochemically neoplastic cells are typically CD3+, CD7+, CD103+, TCRβ+/− cells, CD4−, CD8−, and CD5−, mostly expressing CD30 with CD56 negativity, and demonstrate an activated cytotoxic phenotype (perforin+, granzyme B+, and TIA-1+), reflecting the origin of the tumor from cytotoxic IELs." (PMID 37627888, 2023). "We believe that CD3, CD4, CD5, and CD8 may contribute to PD-1-mediated tumor control." (PMID 36514573, 2022). "CD3, CD4, CD5, and CD8 may contribute to PD-1-mediated tumour control." (PMID 36514573, 2022). "In conclusion, enhanced lipid metabolism and M2 macrophage activation contributed to the immunosuppressive tumor microenvironment and could be potential therapeutic targets in CD5+ non-DE DLBCL." (PMID 36276140, 2022). "Both CD3 and CD5 highlight the background T lymphocytes in the interfollicular areas as well as in between the tumour cells TdT-terminal deoxynucleotidyl transferase is negative in the tumour but is positive in the background residual thymic tissue." (PMID 34419077, 2021). "Of note, sample #15A which according to cytology had few intact tumor cells but a high content of mostly degenerative and inflammatory cells including macrophages (which are PD‐L1‐positive) deviated most from the correlation line for multiple markers, for example, CD4, CD5, CD40, and CD83." (PMID 33768639, 2021). "CD5KO anti-CD5 CAR-T cells showed robust cytotoxicity against CD5+ tumor cell lines at the indicated effector to target ratios, whereas they were not cytotoxic against the CD5− cell lines CCRF-CD5KO, K562, and Raji, demonstrating that the cytolysis was CD5 specific." (PMID 34274536, 2021). "The high prevalence of TZL among Golden Retrievers and corresponding high prevalence of TZUS suggest the genetic basis for developing CD5+CD45− T cells may be fixed among this breed, and different from the genes that control progression to neoplasia in these cells." (PMID 32631225, 2020). "miR‐17 and especially miR‐19b appeared to strongly correlate with the proportion of CD3+ cells in the tumor infiltrate, while miR‐195 consistently showed positive associations with both proportion and density of CD3+, CD4+, CD5+, CD8+ and FOXP3+ cells, but not CD20+ cells." (PMID 33024560, 2020).
tumor (continued). "The neoplasms are negative for the following: CD5, CD23, BCL-2, and TdT." (PMID 29593916, 2018). "In 46 patients (3.1 %) CD117 and/or CD5 could not be evaluated because there were either no vital tumor cells or lost tissue cores during the staining process." (PMID 26643918, 2015). "Interestingly, CD30 and SSBP2 (a tumor-suppressor) expression was frequently negative in CD5+ DLBCL patients." (PMID 25760242, 2015). "Tumor cells, on immunohistochemical staining, expressed positivity for mature B cell markers CD-20, CD-19, CD-10, CD-23, CD-45, and CD-38 but were negative for CD-5,11c." (PMID 26380128, 2015). "Flow cytometry to determine the immunophenotype of the tumor cells typically demonstrates the expression of B-cell associated antigens (CD19, CD20, and CD22), CD45, and CD30 (weak) and an absence of surface immunoglobulins, CD5, and CD10." (PMID 24194994, 2013). "In order to assess whether signaling responses also were altered in tumor-infiltrating T cells in SLL/CLL and MZL, tumor samples were stimulated with IL-2, IL-7 and IL-15 for 15 minutes and phospho-protein levels were evaluated in the CD5+ CD20- T cell fraction." (PMID 23072591, 2012). "Immunohistochemically, tumor cells are usually positive for CD3, CD8, CD56, TIA-1, granzyme B, and perforin, and negative for CD4 and CD5, consistent with the findings in our patient." (PMID 41328359, 2026). "Morphologically, the tumor comprised a subset of lymphoid cells with centrocytic morphology that was positive for CD20, PAX5, CD10, BCL6, and CD23, and negative for CD5 and BCL2." (PMID 40861583, 2025). "Tumor cells typically have an NK-cell phenotype, expressing CD2, CD3ε, and CD56, with no expression of surface CD3, CD4, or CD5." (PMID 38611591, 2024). "The tumor cells were negative expression of CgA, CD56, CK5/6, CK20, Myogenin, MyoD1, Desmin, CEA, S100, CK8/18, CDX2, CD20, CD5, CD3, CD79a, LCA and HMB45." (PMID 38877473, 2024). "Immunohistochemical analysis showed the positivity of the tumor to CD20, CD5, Bcl2, and cyclin D1, while it was negative to CD10 and CD23." (PMID 38698463, 2024). "Briefly, tumor cells in AITL/FHTCL demonstrated a very characteristic immunophenotypic signature with positive expressions of CD2, CD4, CD5, CD45, and heterogeneous CD7 but negative expressions of surface CD3, CD8, CD16, CD56, CD25, CD26, and CD30." (PMID 35299754, 2022). "Immunohistochemistry staining shows monoclonal cytoplasmic defected α-heavy chains that lack light chains and the expression of CD20 positivity on tumor cells, CD138, CD79a, and IgA positivity on plasma cells, and no expressions of CD5 and CD10 on tumor cells." (PMID 35621691, 2022). "Tumor cells in NKCL were consistently negative for CD3, CD4, and CD5 and showed moderate CD2, CD38, CD56, and CD94 and heterogeneous expressions of CD7, CD8, CD16, and CD26." (PMID 35299754, 2022). "The immunophenotype of typical ATLL tumor cells is positive for CD3, CD4, CD5, CD25, CCR4, and CADM1, and negative for CD7 and CD8." (PMID 35625999, 2022). "Immunohistochemistry revealed that tumor cells were positive for CD20, BLC6, BLC2, and c-MYC and negative for CD10, MUM1, and CD5." (PMID 35334633, 2022). "Immunohistochemistry showed that most of the tumor cells in MEITL were positive for CD3(20/20), CD8(17/20), CD43(19/20), and CD56(15/20), but negative for CD5(20/20)." (PMID 34895266, 2021). "T-cell-derived tumor cells are positive for surface CD3+, CD5+, CD4+, or CD8+, or negative for both." (PMID 34830926, 2021). "The tumor cells are positive for CD45, CD30, CD15, MUMi, and Ki-67 (80%) and negative for CD20, PAX-5, CD79a, CD3, CD5, CD10, BCL6, BCL2, EMA, ALK-1, and CD138." (PMID 34900354, 2021). "Immunohistochemically, the tumor cells were negative for CD20, CD79a, CD3, CD5, c-kit, CD34, and TdT and positive for myeloperoxidase, CD33, CD68, and CD163." (PMID 34970464, 2021).